CD14 (CD14 molecule)
Diseases named in the same sentence as CD14 in open-access papers (continued):
Sharing a sentence is not in itself a finding about the gene and the disease.
cervical carcinoma (9 papers, 2006 to 2023). A carcinoma arising from either the exocervical squamous epithelium or the endocervical glandular epithelium. "For instance, infiltration of CD40+ macrophages in CRC and of CD14+CD163− macrophages in cervical cancer were associated with a favorable prognosis." (PMID 24723924, 2014). "In cervical cancer, high frequencies of regulatory T cells (Tregs) and immunosuppressive PD-L1+CD14+ antigen-presenting cells dominate the microenvironment of tumor-positive lymph nodes (LN+)." (PMID 26431490, 2015). "In cervical cancer, the presence of macrophages with the M2 phenotype (CD14+CD163+PD-L1+) may be a factor that decreases patient survival." (PMID 37048119, 2023). "We hypothesized that most IDO-positive immune cells were monocytic MDSCs or tumor-associated macrophages and tried to identify these cells using multicolor fluorescent immunohistochemistry for IDO, CD14, and HLA-DR in PT section from six cervical cancer patients." (PMID 30050535, 2018). "Accordingly, a study with human cervical carcinoma lines showed that tumor-derived IL-6 and PGE2 were responsible for skewing monocyte differentiation toward a CD14+CD163+ M2-type phenotype, and that this was reversible upon co-incubation with Th1 cells." (PMID 24723924, 2014).
dementia (9 papers, 2011 to 2024). Loss of intellectual abilities interfering with an individual's social and occupational functions. "Marginal associations (p ≤ 0.05) were observed for CD5L and CD14 with incident dementia (HR = 1.20 per SD unit increase in CD5L level; 95% CI = (1.03, 1.41), p = 0.02; (HR = 1.20 per SD unit increase in CD14 level; 95% CI = (1.00, 1.44), p = 0.05)." (PMID 36083988, 2022). "Blood CD16+ monocytes may be also more likely to be infected with HIV-1, and in a study performed during the pre-ART era, it was found that numbers of CD14+CD16+ monocyte are elevated in individuals with HIV-associated dementia, which is associated with decreased survival." (PMID 26829391, 2016). "Monocytes with increased expression of CD14 and CD69 have been reported in HIV-associated dementia and culture supernatants from the latter were shown to induce apoptosis in human brain aggregates." (PMID 24341794, 2013). "CD163 co-expression on CD14+CD16++ monocytes has been proposed as a useful biomarker for HIV-1 disease progression and the presence of HIV associated dementia." (PMID 21625498, 2011). "In addition to CD14, CD40L, and MPO relate to the executive function neuropsychological testing domain; CD5L and sRAGE relate to global and regional MRI markers of brain atrophy; CD5L shows marginal association with dementia, and AD dementia." (PMID 36083988, 2022). "With regard to PB changes, CD14+CD16+ monocyte levels were increased in ALS patients compared with dementia (7.94%, IQR 4.14–10.87, P = 0.007) patients, but not in PPMS patients (8.42%, IQR 5.92–12.97, P = 0.113)." (PMID 34405141, 2021).
endometriosis (9 papers, 2017 to 2025). The growth of functional endometrial tissue in anatomic sites outside the uterine body. "Moreover, endometriosis-associated changes in the macrophage subtypes occurred only in the CD14+low/CD68+low subpopulation." (PMID 32572831, 2020). "Here, we have shown that endometriosis is associated with changes in macrophage activation, with a shift from a MΦ1 to a MΦ2 type of immune response in the CD14+low/CD68+low subpopulation, indicating some plasticity of the cells in the development of the disease." (PMID 32572831, 2020). "Our data revealed significantly higher intracellular mTOR and AKT expression in TAMs (CD14+) and epithelial cells from endometriosis patients compared to HGS-OC." (PMID 40723209, 2025). "Consistent with our previous reports, we identified a predominant M2 phenotype (CD14+/CD163+) in the peritoneal fluid of patients with endometriosis." (PMID 40723209, 2025). "Nine of the proteins were identified as being statistically significant between the endometriosis patients and healthy controls with a p value < 0.05 [6Ckine, CD14, ENA-78, I-TAC, LAP (TGF-β), NrCAM, RAGE, TARC, TNF-β]." (PMID 31333337, 2019). "The concentration of leukocytes in the PF, the percentage of cells expressing CD45+/CD14+, and the percentage of PF macrophages expressing the HLA-DR antigen were significantly higher in patients with stages I and II endometriosis." (PMID 29226157, 2017). "Regarding the intracellular markers of the metabolic mTOR pathway, we found that the intracellular levels of mTOR and AKT in macrophages (CD14+) isolated from the ascitic fluid were significantly higher in endometriosis than in papillary serous ovarian cancer (p = 0.001 and p = 0.002, respectively)." (PMID 40723209, 2025). "Conversely, endometriosis showed a dominant M2 profile (CD14+/CD163+), elevated intracellular mTOR and AKT expression in both TAMs and epithelial cells (p < 0.01), and significantly higher ascitic ROS and free iron levels (p = 0.047 and p < 0.0001, respectively)." (PMID 40723209, 2025). "Our study confirms and further extends the observations of these earlier studies, showing that the increase in the relative abundance of the MΦ2 subtype and the corresponding decrease of the MΦ1 subtype in endometriosis are limited to the CD14+low/CD68+low pMΦ subpopulation." (PMID 32572831, 2020). "Therefore, we examined the distribution and abundance of the MΦ2a (CD80−/CD163+/CD206+) and MΦ2b (CD80−/CD163+/CD86+) subtypes in controls and endometriosis in the CD14+low/CD68+low and CD14+high/CD68+high subpopulations." (PMID 32572831, 2020). "Additionally, we identify a mixed MΦ1/MΦ2 subtype that is only decreased in the CD14+low/CD68+low pMΦ subpopulation in endometriosis." (PMID 32572831, 2020). "To conclude, in this study, we have shown that changes in pMΦ polarization in endometriosis patients are limited to the CD14+low/CD68+low pMΦ subpopulation, and that these changes are coupled with increases in Th2 and Treg cells in a switch to a type 2 immune response." (PMID 32572831, 2020). "We found that the mean fluorescence intensity of CD14 + macrophages was significantly lower in endometriosis samples than that of control samples (139.6 ± 17.1 vs. 410.6 ± 92.0, P = 0.02), indicating that the phagocytic ability of macrophages was decreased in peritoneal fluid of endometriosis." (PMID 34039410, 2021). "In this study, we have identified the CD14+low/CD68+low pMΦ subpopulation as that that undergoes changes in MΦ polarization in endometriosis, but further characterization of this subpopulation will be required before such targeted therapies could be trialled as a treatment for the disease." (PMID 32572831, 2020). "The stratification analysis suggests indeed a potential alteration in the function or phenotype of CD14+/CD16+ monocytes, CD4 CTLs, and γδt in endometriosis." (PMID 39684780, 2024).
endometriosis (continued). "In patients with endometriosis, a significantly higher (p < 0.0001) percentage of PF cells expressing CD45+/CD14+ was found, as compared to the reference group." (PMID 29226157, 2017). "In both women with and without endometriosis, the relative abundance of CD14+low cells was significantly lower compared with that of CD14+high cells (2.5 times for controls, p = 0.0002 and 1.7 times for endometriosis, p = 0.0005 respectively, middle)." (PMID 32572831, 2020). "Decrease of non-classical monocyte CD14+CD16+TLR2+ values below their prognostic value has good discriminative power between endometriosis patients with and without adhesion." (PMID 32751735, 2020). "In our study, the levels of nonclassical monocytes CD14+CD16+TLR2+ in patients with endometriosis seem to have good discrimination power between endometriosis patients with and without adhesions." (PMID 32751735, 2020). "The CD14+low/CD68+low subpopulation showed a higher proportion of MΦ1 cells (8.6 times, p = 0.0042 for controls and 5.35 times, p = 0.005 for endometriosis) and a lower proportion of MΦ2 cells (1.8 times, p < 0.0001 for both controls and 2.0 times, p < 0.0001 for endometriosis) (bottom)." (PMID 32572831, 2020). "Our results show that several mRNAs and pathways related to immune function, such as IL-1B, CXCR4, IL-7R, STAT4, CD14, and CCR5, as well as the FoxO signaling pathway, the Jak-STAT signaling pathway, and the NF-kappa B signaling pathway, have significant correlations with endometriosis." (PMID 38203209, 2023). "Similar to the mouse, our data indicates that one pMΦ subpopulation, the CD14+low/CD68+low cells, behaves abnormally in women with endometriosis, which may contribute to an impaired immune response after the initial development of endometriosis lesions." (PMID 32572831, 2020). "We first compared the relative abundance of MΦ1, MΦ1/MΦ2 and MΦ2 macrophages present in the CD14+low/CD68+low subpopulation in women with and without endometriosis." (PMID 32572831, 2020). "The expression level of CD14 and CD68 was correlated, with contour plots revealing distinct CD14+low/CD68+low and CD14+high/CD68+high subpopulations in both women with and without endometriosis (right)." (PMID 32572831, 2020). "We compared CD14+ cells to SSC-A revealing a CD14+low and CD14+high subpopulation that was present in the PF of both women with and without endometriosis (left)." (PMID 32572831, 2020). "Comparison between participants without endometriosis (n = 5) and participants with endometriosis (n = 4) with high serum JUP values (>220 ng/mL) identified nine DEGs (HBB, HBA1, HBA2, and RGPD2 in CD14+ monocytes; CH25H, HBB, LTB, and KLRC1 in γδt; IFIT2 in NK-CD56bright and JUN in Treg)." (PMID 39684780, 2024). "However, the relative abundance of this mixed MΦ1/MΦ2 subtype did not significantly differ between the CD14+low/CD68+low and CD14+high/CD68+high subpopulations of macrophages in either women with or without endometriosis (bottom)." (PMID 32572831, 2020). "This was confirmed by cells in the CD14+high subpopulation showing a significantly higher CD68 mean fluorescence intensity (MFI) than cells in the CD14+low subpopulation for both women with and without endometriosis, indicating that CD14 and CD68 levels are highly correlated in pMΦ (bottom)." (PMID 32572831, 2020).
endothelial dysfunction (9 papers, 2017 to 2025). In vascular diseases, endothelial dysfunction is a systemic pathological state of the endothelium (the inner lining of blood vessels) and can be broadly defined as an imbalance between vasodilating and vasoconstricting substances produced by (or acting on) the endothelium. "Since endothelial dysfunction is an early step in the atherosclerotic process, this association is not surprising and it fits well with our previous finding of a close association between soluble CD14 and ADMA in HIV-infected persons on cART." (PMID 28356058, 2017). "And YKL-40 is expressed in the development of endothelial dysfunction, during the differentiation and maturation of CD14 + monocytes to CD14−, CD16 + macrophages." (PMID 33446257, 2021). "SLE patients showed increased thickness of carotid arteries and endothelial dysfunction when compared to controls by IMT and FMD, respectively; IMT data correlated positively with an increase in the frequency of CD14+CD16++ subpopulation." (PMID 28546658, 2017). "The elevated CD14+/CD16+ monocyte count in patients with CKD was positively correlated with the presence of apoptotic endothelial microparticles, suggesting that a link exists between elevated CD14+/CD16+ and endothelial dysfunction in CKD." (PMID 31547340, 2019). "Thus, higher levels of CD14+CD16hi monocytes may be rather a marker of endothelial dysfunction in patients without severe coronary stenosis." (PMID 33854919, 2020). "Thus, it could be proposed that CD14+CD16++ monocytes are related to atherosclerosis in SLE patients; however, it is not clear whether these cells could be involved in the endothelial dysfunction that occurs in this disease." (PMID 28546658, 2017).
Hyperglycemia (9 papers, 2016 to 2025). An increased concentration of glucose in the blood. "In this study, the increased proportion of CD14+ cells in the villous region of GDM placentas suggests enhanced recruitment or persistence of monocyte/macrophage lineage cells in response to hyperglycemia." (PMID 41303355, 2025). "To evaluate CD14+ M2a macrophages in the term pregnant women with uncontrolled hyperglycemia throughout pregnancy, we calculated CD14+/DC-SIGN+ macrophages in the placenta of the pregnant women in the uncontrolled T2DM and the normal groups." (PMID 35386706, 2022). "First, we conducted univariate logistic regression analyses to identify potential risk factors for VH-TCFA using the presence of DM, the MAGE score, time in hyperglycemia, and CD14++CD16+ monocyte counts." (PMID 28789689, 2017). "We show that short‐term hyperglycemia decreases IL‐6 expression in CD14++CD16+ intermediate monocytes and IL‐17A expression." (PMID 27042306, 2016). "To evaluate hyperglycemia-induced lipid accumulation leading to monocyte infiltration, we performed double immunohistochemistry for lipid accumulation staining using perilipin and monocyte infiltration using monocyte marker CD14." (PMID 36829889, 2023). "In this study, the increase in cells expressing CD14+CD95+ and apoptosis due to hyperglycemia and low-grade inflammation could alter the functional activity of colostrum macrophages." (PMID 36289594, 2022). "Hyperglycemia exerts also a negative impact on CD34+CD14+ and CD34+CD14- circulating proangiogenic cells by inhibiting the secretion of the angiogenic microRNA126 within exosomes." (PMID 30327618, 2018).
lung fibrosis (9 papers, 2018 to 2026). "Higher proportion of S100A9+CD163– cells among CD14+CD16– MNs was found to be associated with lung fibrosis." (PMID 37561593, 2023). "Patients with idiopathic pulmonary fibrosis in the Yale cohort had higher proportions of CD14+ monocytes (of PBMCs) than healthy controls (p=0·014), with percentage of CD14+ cells increasing as mortality risk increased (n=20)." (PMID 30935881, 2019). "Additionally, the six high-risk patients with idiopathic pulmonary fibrosis had more CD14+ monocytes than the nine low-risk patients (p=0·049)." (PMID 30935881, 2019). "In this context, we found that both CD14+ and CD14+HLA-DR+ PBMCs from PC patients with signs of lung fibrosis expressed higher levels of AIM2 and confirmed the release of IL-1α and TGF-β after its triggering." (PMID 35844548, 2022). "CD14 and LBP are mediators of lung inflammation that are produced in response to infectious processes and LRG1 is a hallmark of risk for lung fibrosis assessment." (PMID 35884998, 2022). "Moreover, the responsiveness of AIM2 correlated with higher expression of the receptor in circulating CD14+ cells in PBMCs from patients with signs of lung fibrosis." (PMID 35844548, 2022). "Increased CD14 + classical monocytes in the peripheral blood correlate with poor outcomes in patients with IPF14, and they differentiate into profibrotic macrophages, which contribute to pulmonary fibrosis." (PMID 36797265, 2023). "Additionally, certain subgroups of CD14 + CD16 + monocytes have also demonstrated a protective effect, which further confirms the complex role of immune cells in modulating pulmonary fibrosis." (PMID 38206731, 2023). "In contrast, AIM2 expression on circulating CD14+ PBMCs from PC patients without signs of lung fibrosis had much lower expression of AIM2 and lower levels of cytokine release." (PMID 35844548, 2022). "In our validation analysis of flow cytometry data for 45 patients with idiopathic pulmonary fibrosis from the COMET trial, absolute count of CD14+ monocytes was significantly higher in patients with progressive disease compared with those with non-progressive disease (p=0·025)." (PMID 30935881, 2019). "Here, we examined how the inhibition of multiple TLRs affects pulmonary fibrosis using a novel synthetic receptor activator of nuclear factor κB ligand (RANKL) partial peptide, MHP1-AcN, which could suppress TLR2, 3, 4, 7, and 9 signaling through CD14 and RANK." (PMID 35864207, 2022).
neuroblastoma (9 papers, 2006 to 2023). Neuroblastoma (NB) is the most common solid, extracranial childhood tumor. "Intriguingly, primary human monocytes polarized into suppressive CD14+CSF-1R+ M-MDSC upon co-culture with neuroblastoma cells, mediated by tumor-originating M-CSF and attenuated through CSF-1R blockade." (PMID 38087370, 2023). "Peripheral blood macrophages of patients with neuroblastoma (n = 38) and healthy individuals (control group, n = 37) were labelled (CD14+/CD16+) and assessed for TKTL1, Apo10 and GD2 using the EDIM technology." (PMID 35864157, 2022). "We found that the expression of both BTK and monocyte marker CD14 is elevated in various neuroblastoma cohorts compared to benign neurofibroma (Miller, N = 86)." (PMID 33669187, 2021). "We detected the significantly correlated expression of M2 TAMs marker genes (CD163, CD204, CD206) and M-MDSC marker genes (CD11B, CD14, CD33) in the high-risk neuroblastoma examined, suggesting that the various numbers of M2 TAMs and MDSCs are present in the high-risk neuroblastoma TME." (PMID 33968044, 2021). "Furthermore, we found that high-risk primary neuroblastoma tumors contain CD68+ tumor-associated monocytes/macrophages (TAMs) producing IL-6 and that bone marrows with neuroblastoma metastases include CD33+ CD14+ monocytic cells, which also express IL-6." (PMID 23982484, 2013). "NB-1 neuroblastoma cells express TLR4, MD2, CD14 and MyD88, which are required for LPS signaling." (PMID 17156435, 2006).
acute respiratory distress syndrome (8 papers, 2021 to 2025). Progressive and life-threatening pulmonary distress in the absence of an underlying pulmonary condition, usually following major trauma or surgery. "For instance, following tetraspanin capture, CD14 has been shown to be a marker of acute respiratory distress syndrome." (PMID 37333992, 2023). "In a study on acute respiratory distress syndrome (ARDS), RBP7 was found to be closely associated with CD14 cells, and the high expression of TYMS in both CD14 and B cells suggests a synergistic relationship in regulating immune responses in ARDS." (PMID 41301068, 2025).
allergic rhinitis (8 papers, 2012 to 2025). Inflammation of the nasal mucous membranes caused by an IgE-mediated response to external allergens. "This study aimed to determine the association between C-159T polymorphism in the CD14 gene promoter region and serum CD14 levels and the risk of Allergic rhinitis Egyptian patients and to test the validity of serum CD14 level measurement in predicting AR." (PMID 37286630, 2023). "CD14 C-260T polymorphism has been reported to be associated with some immune-related diseases, such as allergic rhinitis, pediatric asthma and juvenile idiopathic arthritis, most in Asians." (PMID 23049772, 2012). "Additionally, CD14 on CD14+ CD16+ monocytes further contributes to the development of allergic rhinitis." (PMID 39399526, 2024).